GDF15 (growth differentiation factor 15)
Diseases named in the same sentence as GDF15 in open-access papers (continued):
Sharing a sentence is not in itself a finding about the gene and the disease.
chronic kidney disease (continued). "Elevated GDF-15 concentrations have been associated with a greater decline in eGFR, renal disease progression, and incidence of chronic kidney disease (CKD)." (PMID 39780955, 2024). "Although GDF-15 protects against aging-mediated systemic inflammatory responses, GDF-15 concentrations are reported to be positively associated with cardiovascular disease and chronic kidney disease (CKD)." (PMID 37371667, 2023). "For chronic kidney disease, one study demonstrated that circulating levels of plasma GDF-15 were strongly correlated with the intrarenal expression of GDF-15 and was markedly associated with an increased risk of CKD progression." (PMID 35204349, 2022). "Circulating GDF15 levels have been shown to strongly correlate with increased risk of chronic kidney disease (CKD) progression." (PMID 30542297, 2018). "The association was strongest in elderly patients, in those with chronic inflammatory disorders, and those with chronic kidney disease, where GDF-15 correlated with CIMT, atherosclerotic plaque, or coronary calcification." (PMID 41597417, 2026). "Reduced renal function also increases GDF-15 serum concentration, particularly in patients with chronic kidney disease." (PMID 41597417, 2026). "In kidney pathophysiology, both plasma and urinary GDF-15 levels increase in acute and chronic kidney disease, reflecting ongoing inflammation, oxidative stress, and tissue injury." (PMID 41157213, 2025). "Another study found that serum GDF15 levels were higher in Black people with chronic kidney disease in South Africa compared to the White racial group with chronic kidney disease." (PMID 38965822, 2024). "Regarding kidney functions, GDF15 has been involved in different pathologies such as chronic kidney disease, diabetic nephropathy, renal cancer, and so on." (PMID 38892145, 2024). "All together, these different studies indicate that GDF15 is elevated during acute and chronic kidney disease and protects the kidney, mainly, by limiting the inflammation." (PMID 38892145, 2024). "Lastly, GDF15 was also selected for this study, as it serves as a marker of mortality in chronic kidney disease and its level correlates with pulmonary fibrosis." (PMID 38132468, 2023). "In chronic kidney disease, urine GDF15 levels have already been shown predictors of mortality with an AUC of 0.95." (PMID 37891738, 2023). "The diabetic group had a significantly higher prevalence of chronic kidney disease; higher serum HbA1c, GDF15, and urine albumin/creatine ratio." (PMID 35683420, 2022). "GDF15 levels were significantly elevated in end-stage renal disease patients compared to healthy individuals (2844 (IQR 2087, 3361) pg/ml vs. 384 (IQR 307, 487) pg/ml, p < 0.001)." (PMID 32375259, 2020). "Over the last years, some studies have focused in the prognostic utility of GDF-15 in chronic kidney disease population." (PMID 33419237, 2020). "Until now, systemic GDF15 levels have been shown to correlate with the progression of chronic kidney disease (CKD)." (PMID 32977372, 2020). "GDF15 predicts incident chronic kidney disease (CKD) and decline in renal function in established CKD." (PMID 32310257, 2020). "Since increased GDF15 levels are strongly associated with cardiovascular disease and all-cause mortality, it is not surprising that GDF15 was postulated to be an independent serum marker of mortality in chronic kidney disease (CKD) and hemodialysis patients." (PMID 32375259, 2020). "This is compatible with the previous paper showing that preoperative GDF-15 levels in patients undergoing CABG were positively associated with age, chronic renal failure, and high NT-proBNP." (PMID 31581569, 2019). "The aim of the study was to assess the GDF-15 and iron status in patients with early stages of chronic kidney disease with particularly emphasis on elderly population." (PMID 27043030, 2016).
chronic kidney disease (continued). "In patients with CAD undergoing PCI with stent implantation, GDF-15 is determined by advanced age, acute and chronic hyperglycemia, inflammation and chronic kidney disease." (PMID 27056183, 2016). "GDF-15 is also patented for the diagnosis of kidney injury after surgery, prediction of kidney failure after heart surgery, and detection the prognosis of chronic kidney diseases." (PMID 26273671, 2015). "GDF-15 expression is up-regulated in chronic kidney disease and represents a novel independent serum marker of mortality." (PMID 25171167, 2014). "This is in agreement with previous results showing that GDF-15 was a novel independent serum marker of mortality in chronic kidney disease." (PMID 25171167, 2014). "In addition, GDF-15 is known to be elevated in a wide range of systemic conditions, including cardiovascular disease, chronic kidney disease, and malignancy, reflecting its role as a general stress-responsive cytokine rather than a disease-specific marker." (PMID 41515626, 2026). "Additionally, GDF15 has emerged as a predictor of chronic kidney disease progression and renal function deterioration in patients with preexisting renal pathology." (PMID 40723863, 2025). "Furthermore, GDF-15 serves as a predictor for long-term renal dysfunction, chronic kidney disease progression, and mortality, thereby enhancing its utility in clinical decision-making." (PMID 40243457, 2025). "Furthermore, elevated levels of GDF-15 are associated with adverse renal outcomes and may serve as a potential biomarker for predicting the progression of chronic kidney disease (CKD) and its cardiovascular complications." (PMID 40564142, 2025). "Additionally, GDF15 serves as a predictor of chronic kidney disease progression and renal function decline in patients with existing kidney pathology." (PMID 40806859, 2025). "For another example, GDF-15 levels are found to be correlated with an increased risk of chronic kidney disease progression or albuminuria in patients with T2DM, while animal study suggested that GDF-15 could be reno-protective." (PMID 36742413, 2023). "However, the detail effect of GDF15 on cardiovascular system in patients with chronic kidney disease (CKD) needs detail analysis." (PMID 33567936, 2021). "The baseline analysis revealed that chronic kidney disease (HR 28.13, 95%CI 4.84–163.38), lung fibrosis on high resolution computed tomography (HR 4.36, 95%CI 1.04–18.26) and GDF-15 concentration (unit HR 1.0006, 95%CI 1.0002–1.0010) were independent predictors of MACE occurrence." (PMID 34599271, 2021). "In this study, we found that plasma levels of GDF-15 are significantly elevated in children with a renal transplant and in children with chronic kidney diseases compared to healthy children and that plasma GDF-15 levels are strongly associated with kidney function." (PMID 32089755, 2020). "Hence, the aim of this study is to define the determinants of GDF-15 in a cohort of advanced chronic kidney disease patients and evaluate its potential use as a predictor of survival after transplant." (PMID 33419237, 2020). "Elevated circulating GDF-15 has been related to incident kidney disease, and it is suggested that it might be useful in predicting the progression of chronic kidney disease, years before clinical onset of the disease." (PMID 32089755, 2020). "In patients with chronic kidney disease, serum concentration of GDF-15 is elevated." (PMID 27043030, 2016). "The aim of the study was to assess GDF-15 and iron status in patients in early stages of chronic kidney disease with a particular emphasis on elderly population in association of classic iron status parameters with novel iron homeostasis biomarkers and inflammatory parameters." (PMID 27043030, 2016). "In patients with end-stage renal disease, GDF-15 correlation with hsCRP has also been reported." (PMID 27043030, 2016).
chronic kidney disease (continued). "We calculated the area under the receiver operating characteristic (ROC) curve to evaluate the effectiveness of our GDF15 prediction model for patients with chronic kidney disease (CKD)." (PMID 35683420, 2022). "In patients with chronic kidney disease without signs of HF at recruitment, high Gal-3 levels were associated with early symptomatic changes of HF, although with a hazard ratio lower than that of growth differentiation factor-15 (GDF-15)." (PMID 33287402, 2020). "In a multivariate regression analysis advanced age, DM, acute hyperglycemia (AHG), CRP and chronic kidney disease (CKD) were independent predictors of elevated GDF-15 levels (P < 0.05)." (PMID 27056183, 2016). "In addition, GDF-15 is also a novel independent serum marker of mortality in chronic kidney disease (CKD), and combining this marker with other established predictors of mortality may help to identify individuals at high risk for developing CKD." (PMID 25171167, 2014). "Moreover, serum/plasma GDF15 concentrations predicted renal impairment in the course of diabetic nephropathy and incidence of chronic kidney disease (CKD) in the general population, whereas elevated serum GDF15 increased the risk of CKD progression." (PMID 40076962, 2025). "Therefore, GDF-15 is not heart-specific and is, e.g., associated with chronic kidney diseases." (PMID 38398274, 2024). "Expression of both GDF-15 and TGF-β have been reported to significantly increased in chronic kidney disease and in mice infused with angiotensin II." (PMID 39394174, 2024). "The other three studies investigating the relationship between GDF-15 and coronary artery calcification all involved specific patient populations: patients with chronic obstructive pulmonary disease (COPD), end-stage renal disease, and psoriasis." (PMID 37548881, 2024). "In some disease states, especially in late stage cancer, chronic renal failure and severe congestive heart failure, MIC-1/GDF15 serum levels frequently rise to 10,000 to 20,000 pg per ml and occasionally to much higher levels." (PMID 24971956, 2014). "In chronic kidney disease (CKD), GDF15 is also predictive of mortality." (PMID 31853550, 2020). "By contrast, GDF15 levels are greatly enhanced in a number of disease states, including cancer, cardiovascular disease and chronic kidney disease, pointing towards a more obvious role as a non-physiological anorectic signal." (PMID 32723474, 2020). "The relationship between growth differentiation factor 15 (GDF-15) and the development of chronic kidney disease (CKD) is still unclear." (PMID 34706669, 2021). "Interestingly, renal transplantation in patients established on hemodialysis reduces but does not normalize circulating GDF15 levels, suggesting that elevated GDF15 in end-stage renal disease is only partly driven by the uremic milieu." (PMID 32310257, 2020). "In a previous study that evaluated older patients with chronic kidney disease, it was observed that there was a correlation between age and GDF-15 levels, which could serve as a precedent to evaluate the relationship between high levels of GDF-15 and frailty in extensive cohorts." (PMID 35740447, 2022). "However, some inconsistent studies showed that serum GDF-15 level was not influenced by the presence of AF in patient with HF from the BIOSTAT-CHF trial and patients with chronic kidney disease (CKD) from the CRIC study." (PMID 33115406, 2020).
colorectal cancer (73 papers, 2007 to 2026). A primary or metastatic malignant neoplasm that affects the colon or rectum. "Increased serum levels of GDF15 have been significantly associated with a higher number of colorectal adenomas and an elevated risk of recurrence for both adenomas and colorectal cancer (CRC)." (PMID 40868185, 2025). "In particular, we knocked down LDHA and LDHB to lower histone lactylation levels, and then we restored GDF15 in LDH-deficient colorectal cancer cells." (PMID 40775002, 2025). "The upregulation of GDF15 was reported correlate with an increased risk of recurrence and a decreased overall survival of colorectal cancer." (PMID 34361106, 2021). "Mesothelin (MSLN) is reportedly associated with the prognosis of colorectal cancer, and growth differentiation factor 15 (GDF15) is reportedly associated with the recurrence and 5-fluorouracil resistance of colorectal cancer." (PMID 34361106, 2021). "In colorectal cancer, a meta-analysis built upon eight individual studies concluded that higher GDF-15 expression is associated with worse overall survival, with a pooled hazard ratio (HR) of 2.09 [95% confidence interval (CI): 1.47–2.96]." (PMID 32508832, 2020). "In patients with metastatic melanoma and colorectal cancer higher serum GDF-15 levels were strongly associated with reduced overall survival." (PMID 30646851, 2019). "Previous studies have reported that GDF15, a cytokine associated with cell growth and differentiation, might effectively predicated the prognosis of colorectal cancer patients as a ferroptosis-related gene." (PMID 35860670, 2022). "To test the hypothesis that GDF15 may be associated with an increased metastatic capacity of colorectal cancer, we detected the expression of GDF15 in a cohort of 234 primary colorectal cancer samples using immunohistochemistry (IHC)." (PMID 26497212, 2016). "Although various studies have demonstrated that growth differentiation factor 15 (GDF15) might be a potential diagnostic and prognostic marker in colorectal cancer (CRC) patients, the results are inconsistent and the statistical power of individual studies is also insufficient." (PMID 26990020, 2016). "GDF15 is overexpressed in several solid malignancies, including colorectal cancer, non–small cell lung cancer (NSCLC), urothelial carcinoma, and renal cell carcinoma." (PMID 40354065, 2025). "Taken together, we confirmed previous observations on NAG-1/GDF15 expression in various colorectal cancer cells and showed that NAG-1/GDF15 plays a key role in regulating protein synthesis." (PMID 40316530, 2025). "Apigenin, a kind of dietary flavonoids, exhibits anticancer properties by emerging as particularly effective in suppressing colorectal cancer growth through up-regulation of GDF15." (PMID 40837873, 2025). "In contrast, others have extensively studied NAG-1/GDF15 as a tumor suppressor gene in colorectal cancer." (PMID 40316530, 2025). "Given the overexpression of GDF15 in colorectal cancer, NSCLC, and urothelial carcinoma, along with the prognostic association and high unmet clinical need, these tumor types were selected for the initial clinical study." (PMID 40354065, 2025). "Next, stable cell lines were generated using SW480 cells, which exhibit low levels of endogenous NAG-1/GDF15 expression compared to other colorectal cancer cell lines used in this study." (PMID 40316530, 2025). "Further analysis of β-catenin and NF-κB target genes showed a decrease in their expression with NAG-1/GDF15 overexpression in colorectal cancer cells." (PMID 40316530, 2025).
colorectal cancer (continued). "When comparing the cell lysate and the media, we observed that the ratio of mature NAG-1/GDF15 to pro-NAG-1/GDF15 varied among the different colorectal cancer cell lines." (PMID 40316530, 2025). "In conclusion, our research shows that GDF15 functions as an oncogene in human colorectal cancer and is directly controlled by H3K18 lactylation." (PMID 40775002, 2025). "This study highlights the critical roles of NAG-1/GDF15, EpCAM, β-catenin, and NF-κB in the pathophysiology of colorectal cancer (CRC)." (PMID 40316530, 2025). "Increased levels of circulating GDF15 are seen in patients with various types of cancer, for example, prostate and colorectal cancer." (PMID 37223632, 2023). "An atlas of the human transcriptome reported that GDF-15 mRNA expression was relatively low in pancreatic cancer compared to prostate, urothelial, renal, melanoma, and colorectal cancers." (PMID 34638326, 2021). "Other investigations on prostate and colorectal cancer indicated that GDF-15 promoted metastasis through cooperating with EGR1 or TGFβ-mediated EMT." (PMID 34070192, 2021). "When included in a multi-marker panel (that also included MIC-1/GDF15), the AUC was above 0.8 for colorectal cancer and reached 0.6 for advanced adenomas in two of the three studies." (PMID 34503217, 2021). "Large-scale analyses of biomarkers from cancer samples showed elevated expression of GDF15 in the tissue or serum of patients with prostate, breast and colorectal carcinomas." (PMID 34681812, 2021). "Another study has, however, described GDF-15 dependent induction of apoptosis in colorectal cancer cells and suggested GDF-15 to act as a tumor suppressor." (PMID 32508832, 2020). "Here, we present that hypoxic exposure causes endoplasmic reticulum stress and activates the unfolded protein response pathways, which drives GDF15 expression in colorectal cancer cells." (PMID 32076610, 2020). "A clear association between increased GDF-15 levels and shorter OS was observed in patients with DST (HR = 2.34), as well as in colorectal cancer (HR = 2.27)." (PMID 30808336, 2019). "Elevated serum levels of GDF15 and increased GDF15 tissue expression in patients with metastatic prostate, pancreatic, breast, and colorectal cancer have also been observed." (PMID 31389184, 2019). "Large-scale delineation of biomarkers from cancer samples showed elevated expression of GDF15 in the tissue and serum of patients with prostate, breast and colorectal carcinomas." (PMID 29636108, 2018). "There was a progressive increase in GDF15 levels in those with adenomatous polyps or colorectal carcinoma." (PMID 30542297, 2018). "Macrophage inhibitory cytokine 1 (MIC-1/GDF15) has been characterized as a candidate biomarker for colorectal cancer (CRC) recently." (PMID 28206963, 2017). "Compared with empty vector (EV), GDF15-Flag vector promoted colorectal cancer cell migration and invasion." (PMID 26497212, 2016). "To investigate the molecular function of GDF15 in colorectal cancer, we detected the expression of GDF15 in colorectal cancer cell lines." (PMID 26497212, 2016). "Overall, data from these mice model strongly support the role of GDF15 as a pro-metastatic gene in colorectal cancer." (PMID 26497212, 2016). "GDF15 is a secretory protein, so we detected GDF15 level in plasma from another cohort of 287 colorectal cancer patients and 353 healthy control donors by ELISA." (PMID 26497212, 2016). "The aim of this study was to assess the prognostic value of GDF15 in patients with colorectal cancer (CRC)." (PMID 21468045, 2011). "Altogether, these findings suggest that NAG-1/GDF15 could be an effective molecular target for colorectal cancer treatment, as it simultaneously impacts multiple signaling pathways, potentially generating synergistic anticancer effects." (PMID 40316530, 2025).